CDK5RAP3 (CDK5 regulatory subunit associated protein 3)
Diseases named in the same sentence as CDK5RAP3 in open-access papers (continued):
Sharing a sentence is not in itself a finding about the gene and the disease.
tumor (35 papers, 2011 to 2025). "Through the xCELL algorithm, this study found that ERLIN2 and CDK5RAP3 were significantly associated with many tumor-immune cells." (PMID 38643190, 2024). "Both gain-of-function and loss-of-function experiments indicate that CDK5RAP3 can increase cell proliferation, migration, invasiveness and xenograft tumor growth in HCC cell lines." (PMID 34722315, 2021). "We used xenograft tumour models to evaluate the anticancer properties of CDK5RAP3 in vivo and the potential to regulate the tumour microenvironment." (PMID 35999359, 2023). "The low expression of CDK5RAP3 led to a significant increase in CD206+ cells and a decrease in CD16/32+ cells in tumour tissues, while the high expression of CDK5RAP3 led to a decrease in CD206+ cells and an increase in CD16/32+ cells." (PMID 35999359, 2023). "The results showed that low expression of CDK5RAP3 significantly promoted tumour proliferation in vivo, while the MMP2 inhibitor reversed this phenomenon." (PMID 35999359, 2023). "The number of F4/80+ cells in xenograft tumours with high CDK5RAP3 expression was significantly reduced." (PMID 35999359, 2023). "Some cytokines that play an important role in anti-tumour immunity are significantly enriched in low CDK5RAP3 expression." (PMID 35999359, 2023). "A xenograft tumour model was established to verify the role of CDK5RAP3 in the recruitment of monocytes." (PMID 35999359, 2023). "Western blotting was used to verify the expression of CDK5RAP3 in different xenograft tumour model groups." (PMID 35999359, 2023). "The results of F4/80 staining indicated an increased number of F4/80+ cells in xenograft tumours with low CDK5RAP3 expression." (PMID 35999359, 2023). "Shortly thereafter, the same authors reported that CDK5RAP3 inhibits NF-κB signaling, providing additional evidence for its role in preventing tumor formation." (PMID 35053516, 2022). "Of these, we focused on CDK5RAP3, owing to its previously reported role as a tumor suppressor in hepatocarcinoma." (PMID 35053516, 2022). "On the contrary, another group revealed that CDK5RAP3 functioned as a tumor-suppressor in HepG2 and sk-Hep1 cells." (PMID 35884562, 2022). "Taken together, these data indicate that CDK5RAP3 has a marked relationship with human carcinoma but its precise function seems to vary greatly depending on tumor types, tumor stages or experimental condition." (PMID 34722315, 2021). "In the HCC, CDK5RAP3 expression is markedly decreased in the HCC tissues and cell lines, and its decreased expression is strongly associated with tumor size, histopathological classification, serum α-fetoprotein and poor prognosis." (PMID 34722315, 2021). "In most cases, CDK5RAP3 acts as a tumor suppressor, inhibiting the cell proliferation, migration and invasion, as well as inducing apoptosis." (PMID 34722315, 2021). "Given that cell adhesion and invasion are essential properties of tumor metastasis in malignancies, CDK5RAP3 is also an important participant in tumor metastasis." (PMID 34722315, 2021). "Meanwhile, in vivo studies revealed that diminished CDK5RAP3 levels enhanced xenograft tumor growth and angiogenesis." (PMID 33182370, 2020). "In cells, cell growth and invasiveness indicate that CDK5RAP3 acts as a tumor suppressor by preventing the effects of MCM6." (PMID 31528213, 2019). "Taken together, these data indicate that CDK5RAP3 acts as a tumor suppressor by preventing the effects of MCM6." (PMID 31528213, 2019). "Compared with their respective adjacent non-tumor tissues, protein levels of CDK5RAP3 were significantly decreased in GNEC tissues." (PMID 31728130, 2019).
tumor (continued). "Consistent with our in vitro results, these data confirm that decreased expression of CDK5RAP3 promotes tumor growth and angiogenesis in vivo." (PMID 31728130, 2019). "Decreased CDK5RAP3 expression promotes cellular transformation, xenograft tumor growth, and xenograft tumor vascularity." (PMID 31728130, 2019). "Wound-healing assays, invasion and metastasis assays, tube formation assays, and tumor xenograft transplantation assays were performed to evaluate the effect of CDK5RAP3 on GNEC angiogenesis in vitro and in vivo." (PMID 31728130, 2019). "The ligating enzyme, Ufl1, was shown to interact with CDK5Rap3, a tumor suppressor that regulates the cyclin D1 synthase." (PMID 24921187, 2014). "Cdk5rap3 has been proposed to be a tumor suppressor due to the inhibition of the nuclear factor κB (NF-κB) pathway." (PMID 24921187, 2014). "As a result, inhibition of CDK5RAP3 can potentially be used to restore the expression of this important tumor suppressor expression, providing new molecular targets for the therapeutic intervention in HCC." (PMID 22860085, 2012). "Whether CDK5RAP3 is a tumour activator or an inhibitor depends on the amount of expression in different cancer tumours." (PMID 35509151, 2022). "However, when both genes are simultaneously abrogated, tumor progression is extremely enhanced, and tumor cells acquire resistance to DNA-damaging drugs, a phenotype that resembles our findings related to CDK5RAP3 depletion." (PMID 35053516, 2022). "Here we identify the tumor suppressor CDK5RAP3 as a novel BRCA2 helical domain-interacting protein." (PMID 35053516, 2022). "In addition, based on the present reports, the function of CDK5RAP3 in tumor is depending on cell or tissue type." (PMID 34722315, 2021). "Additionally, they discovered that decreased CDK5RAP3 level promotes xenograft tumor growth and blood vessel density in a HeLa cell-induced xenograft mice model, but also enhances NF-κB-dependent cellular invasion and MMP9 expression in a U2OS cell model." (PMID 34722315, 2021). "In summary, these results suggest that CDK5RAP3 may function as a tumor suppressor for these cancers." (PMID 34722315, 2021). "Consequently, the molecular mechanisms of CDK5RAP3 acting as a tumor suppressor or promotor appear to be complicated and diverse." (PMID 34722315, 2021). "Rather, several studies support the viewpoint that CDK5RAP3 is a tumor promotor." (PMID 34722315, 2021). "In addition, CDK5RAP3 has been proposed to be a tumor suppressor because it inhibits the NF-κB cell survival pathway and its protein level is significantly underexpressed in head and neck squamous cell carcinomas." (PMID 22860085, 2012). "CDK5RAP3 downregulation may therefore lead to the worst possible scenario for tumor progression because it confers resistance to DNA damage agents, reduces genome instability, and increases tumor aggressiveness." (PMID 35053516, 2022). "However, low‐ or high‐level expression makes it controversial that whether CDK5RAP3 is a tumour activator or an inhibitor." (PMID 35509151, 2022).
tumor (continued). "Taking into consideration that both HSF1 and HSP90 are ones of the factors defining tumor growth and tumor resistance to therapeutics, such knowledge is crucial for a rational development that CDK5RAP3 may be examined as a potential target for anticancer therapy." (PMID 33182370, 2020). "When CDK5RAP3 expression is low, MCM6 accumulates abnormally in the nucleus and promotes cell proliferation, suggesting that CDK5RAP3 functions as a tumor suppressor by regulating cell cycle progression." (PMID 41179291, 2025). "Our study demonstrated that low expression of CDK5RAP3 promotes CCL2/CCR2 signalling to regulate the recruitment of monocytes and macrophages to tumour tissues." (PMID 35999359, 2023). "Combining the low CDK5RAP3 and UFM1 expression, analysis of related factors showed that the low expression level of the two was related to tumour size, depth of invasion, lymph node metastasis and TNM staging." (PMID 36387125, 2022). "Similarly, because CDK5RAP3 deficiency could make tumors dependent on HR or SSA repair pathways, it is conceivable that inhibiting HR, SSA or both combined would also be synthetically lethal in tumor cells with low CDK5RAP3 expression." (PMID 35053516, 2022). "Based on the univariate analysis, overall survival was related to BMI, tumour size, TNM staging and combined CDK5RAP3 and UFM1 expression." (PMID 36387125, 2022). "Consequently, CDK5RAP3 may be of importance for disease, especially tumor progression." (PMID 34722315, 2021). "IHC staining of CD31, p-AKT (s473), CDK5RAP3 and VEGFA in xenograft tumor tissues showed that MVD in the CDK5RAP3 overexpression group was lower than in the control group." (PMID 31728130, 2019). "Immunohistochemistry was used to assess the expression of CDK5RAP3 in GNEC tissues and adjacent non-tumor tissues." (PMID 31728130, 2019). "The number of CD206+ cells in xenograft tumours with high CDK5RAP3 expression was significantly less than the number of CD206+ cells in the control group, while CD206+ cells in xenograft tumours with low CDK5RAP3 expression increased significantly." (PMID 35999359, 2023). "Second, CDK5RAP3 is also frequently upregulated in human HCC tissues and cell lines, and this overexpression is closely related to more aggressive phenotype, including more tumor microsatellite formation and extrahepatic metastasis, and poor differentiation." (PMID 34722315, 2021). "In conclusion, our study demonstrates that low expression of CDK5RAP3 in GNEC activates the AKT/HIF-1α/VEGFA signaling pathway, increasing secretion of VEGFA from GNEC cells into the tumor microenvironment and promoting tumor angiogenesis." (PMID 31728130, 2019). "In addition, CDK5RAP3 protein levels were detected in GNEC tissues and respective adjacent non-tumor tissues from 8 additional patients using western blot analysis." (PMID 31728130, 2019). "The results demonstrated that CDK5RAP3 and MCM6 colocalized in the cytoplasm in the adjacent nontumor tissues, while CDK5RAP3 had lowered expression in the tumor tissues, and MCM6 had greater nuclear expression in tumor tissues." (PMID 31528213, 2019). "Furthermore, low expression of CDK5RAP3 is correlated with more advanced TNM stage, increased tumor microvessel density, and poor prognosis." (PMID 31728130, 2019). "Furthermore, low expression of CDK5RAP3 was correlated with more advanced TNM stage, increased tumor microvessel density, and poor prognosis." (PMID 31728130, 2019). "CDK5RAP3 expression score was significantly lower in tumor tissues compared to their respective non-tumor tissues." (PMID 31728130, 2019). "In these paired samples, the CDK5RAP3 expression score was significantly higher in nontumor tissues than in the respective tumor tissues." (PMID 31528213, 2019). "Cells lacking CDK5RAP3 are more prone to cell invasion and exhibit enhanced xenograft tumor growth." (PMID 35053516, 2022).
tumor (continued). "However, we compared the expression of CDK5RAP3 in tumor tissue and adjacent non-tumor tissues by IHC, and found that CDK5RAP3 expression was significantly lower in tumor tissues compared to their respective non-tumor tissues." (PMID 31728130, 2019). "Significantly, AKT activation affects the prognostic value of CDK5RAP3 for overall survival, whereas CDK5RAP3 expression does not affect the prognostic value of AKT, which provides clinical support for the tumor suppression mechanism of CDK5RAP3." (PMID 29540196, 2018).
cancer (17 papers, 2011 to 2024). A tumor composed of atypical neoplastic, often pleomorphic cells that invade other tissues. "In this study, it was initially clarified that ERLIN2 is an anti-cancer factor and CDK5RAP3 is a pro-cancer factor in PCa, and that the expressions of both were significantly correlated with the clinic-pathologic features." (PMID 38643190, 2024). "In short, it is necessary to develop immunotherapy targets for CDK5RAP3 targeting macrophages to provide a broader vision for cancer immunotherapy with more personalized treatment methods." (PMID 35999359, 2023). "But any way, the present findings have provided an opportunity for shedding enormous insight into physiological and pathological actions of CDK5RAP3 and for further interrogating its functions in cancer and other diseases." (PMID 34722315, 2021). "Numerous studies have revealed the potential inhibitory role of the CDK5RAP3 in the context of various cancers." (PMID 34722315, 2021). "CDK5RAP3 is an evolutionally conserved protein that is closely related to the occurrence and development of various cancers." (PMID 29540196, 2018). "Therefore, the present study tentatively suggests that ERLIN2 is a cancer suppressor gene and CDK5RAP3 is an oncogene." (PMID 38643190, 2024). "Research on CDK5RAP3 was meaningful for understanding the mechanism of cancer." (PMID 35509151, 2022). "Again, as a multifaceted protein, whether CDK5RAP3 is involved in more diseases beyond cancer is also a unresolved problem." (PMID 34722315, 2021). "Given that it is considered as a vital satellite component of the UFMylation pathway, CDK5RAP3 may be involved in other diseases besides cancer." (PMID 34722315, 2021). "In addition, the ectopic expression of CDK5RAP3 suppresses cell proliferation, migration, invasion, angiogenesis, xenograft growth, and cancer stem-like cells (CSCs) phenotype, and epithelial-mesenchymal transition." (PMID 34722315, 2021). "On the contrary, other studies have suggested that CDK5RAP3 may play a pro-tumorigenesis role in a couple of carcinomas." (PMID 34722315, 2021). "The activities of CDK5RAP3 vary in different cancer types, reflecting the importance of CDK5RAP3 in tumorigenesis and cancer metastasis, and the specific function of CDK5RAP3 remains unknown." (PMID 29540196, 2018). "However, the pro- and anti-cancer roles of CDK5RAP3 are unclear." (PMID 38643190, 2024). "Hence, the roles of CDK5RAP3 in human cancers remain elusive and controversial." (PMID 34722315, 2021). "However, the function of CDK5RAP3 in cancers remains controversial." (PMID 31061682, 2019). "Thus, all these studies indicate that CDK5RAP3 may also act as an oncogene for these cancers." (PMID 34722315, 2021). "In cancer samples with low CDK5RAP3 protein levels, the proportion of samples exhibiting p-AKT (Ser473) expression was significantly higher than that exhibiting high CDK5RAP3 expression (77.0% vs. 24.0%)." (PMID 29540196, 2018). "In addition, in cancer samples with low CDK5RAP3 protein levels, the proportion of samples exhibiting p-GSK-3β (Ser9) expression was also significantly higher than that exhibiting high CDK5RAP3 expression (64.0% vs. 32.0%)." (PMID 29540196, 2018).
infection (1 paper, 2023). The state of being infected such as from the introduction of a foreign agent such as serum, vaccine, antigenic substance or organism. "In contrast, RNAs related to checkpoint signaling (e.g., CDK5RAP3 and CDC5L) and meiotic cell cycle (e.g., TOP2A) were decreased in the cells infected by Salmonella compared to cells without infection under the aerobic condition." (PMID 37040488, 2023).
metabolic disorders (1 paper, 2021). "Additionally, in a diabetic mouse model, CDK5RAP3 expression is recently found to be downregulated which supports its involvement in metabolic diseases." (PMID 34722315, 2021).
neurodevelopmental disorder (1 paper, 2026). A behavioral and cognitive disorder with onset during the developmental period that involves impaired or aberrant development of intellectual, motor, or social functions. "We investigated the pathogenicity of a homozygous intronic variant in CDK5RAP3, a key UFMylation adapter, in three individuals from two unrelated families with a lethal neurodevelopmental disorder." (PMID 42045457, 2026).
CDK5RAP3 also shares sentences with these, for which no sentence is quoted: lung carcinoma (3 papers); colon cancer (2); colorectal cancer (2); epilepsy (2); glioma (2); autism spectrum disorder (1); clear cell renal cell carcinoma (1); diabetes (1); head and neck cancer (1); hemorrhage (1); inflammatory bowel disease (1); kidney cancer (1); liver cirrhosis (1); liver fibrosis (1); major depressive disorder (1); malignant glioma (1); mastitis (1); melanoma (1); non-small cell lung carcinoma (1); prostate carcinoma (1); schizophrenia (1); triple-negative breast carcinoma (1).